IL12RB2 (interleukin 12 receptor subunit beta 2)
Diseases named in the same sentence as IL12RB2 in open-access papers (continued):
Sharing a sentence is not in itself a finding about the gene and the disease.
tumor (continued). "Compared with normal tissues, only SLURP1 was downregulated in tumor tissues, while the expression levels of DKK1, GAST, IGHM, IL12RB2, STC2, and TNFRSF4 were upregulated in tumor tissues." (PMID 39282247, 2023). "Our previous study also found that well-differentiated tumor tissue had high mRNA expression levels of IL-12Rβ2 and INF-γ, whereas moderately and poorly differentiated tumor tissues had low levels of these markers." (PMID 33415169, 2020). "As expected, NHS–rmIL-12 treatment of irradiated mice engrafted with WT marrow resulted in significant tumor growth delay or cure, but no treatment effect was observed following treatment of irradiated mice engrafted with IL-12Rb2–KO BM." (PMID 35260537, 2022). "In the 4T1-BALB/c syngeneic tumor model, suppression of IL12RB2 reduced metastasis without affecting the growth of the primary tumor." (PMID 30218063, 2018). "This was not due to a direct effect of IL-12 on 4T1 tumour cells, since these cells did not express IL-12Rβ2 and IL-12Rβ1 and their in vitro growth was not affected by IL-12." (PMID 27982126, 2016). "Consistent with reduced Il12rb1 and Il12rb2 expression by primed, SIY-reactive CD8+ T cells in lung TdLNs, SIY-reactive CD8+ T cells from KP.SIY lung tumor–bearing mice bound significantly less IL12-MSA than SIY-reactive CD8+ T cells from flank tumor–bearing mice." (PMID 37669107, 2023). "We identified TNFRSF18, TNFSF4, and IL12RB2 as biomarkers that predict response to NK cell therapeutics in recurrent GBM, which might provide a new treatment strategy for this highly aggressive tumor." (PMID 36694264, 2023). "Although we could not give the direct evidence for the role of IL12RB2 in our study, we could assume that IL12RB2, probably expressed on NK cells, enhanced anti-tumor immunity by increasing T or NK cell cytotoxicity and developing memory T cells under the condition of IL12 production." (PMID 36694264, 2023).
cancer (13 papers, 2012 to 2025). A tumor composed of atypical neoplastic, often pleomorphic cells that invade other tissues. "Apart from T cells, IL-35+ macrophages were able to upregulate IL-12Rβ2 expression on cancer cells and make them more responsive to IL-35, facilitating the activation of JAK2–STAT6 and GATA3, and increased metastasis in mouse models of breast and lung cancer." (PMID 33418929, 2021). "The expression of IL-12Rβ2 and IL-23R on laryngeal tumor cells mediated crosstalk between the cancer cells and tumor-infiltrating lymphocytes and affected the prognosis of laryngeal cancer patients." (PMID 33418929, 2021). "In primary tumors, inflammation-induced EMT upregulates IL12Rβ2, a subunit of the IL-35 receptor, in cancer cells to help them respond to IL-35 during metastasis." (PMID 30218063, 2018). "Collectively, these data indicate that inflammation-induced EMT upregulates the expression of IL12Rβ2 in cancer cells, which is critical for cancer cells to respond to IL-35 from mTAMs to complete metastatic colonization." (PMID 30218063, 2018). "Actually, IL12RB2 has already found to limit cancer growth and thus proven to elicit an effect on its own." (PMID 22509262, 2012). "Knockdown of IL12RB2 in cancer cells abrogated M2 CM-induced JAK activation and MET." (PMID 30218063, 2018). "TNFα upregulated IL12RB2 expression in different cancer cell lines." (PMID 30218063, 2018). "As Il12rb2 mRNA is abundantly expressed in NK cells, it is tempting to suggest that lack of IL-12Rβ2 expression is sufficient to deregulate NK cell immune surveillance, thereby increasing cancer prevalence." (PMID 24586521, 2014). "This revealed a set of genes shared with human eTreg cells from affected sites in JIA, RA, and cancer including BATF, VDR, MICAL2, TOX2, KAT2B, PFKFB3, and IL12Rβ2." (PMID 33976194, 2021). "Additionally, there are very significant differences between the two groups in methylation of specific genes known to be important in UM and in cancer progression in general, including PTEN, NFIA, IL12RB2, RASSF1, and HDAC4." (PMID 33092094, 2020). "The top genes were IL12RB2, PTHLH, and SCL7A11, which are all involved in cancer biology." (PMID 26029238, 2015).
infection (8 papers, 2017 to 2024). The state of being infected such as from the introduction of a foreign agent such as serum, vaccine, antigenic substance or organism. "Il12rb2−/− mice were more susceptible to C. rodentium infection early on during the course of infection (3 days post infection [d.p.i.]) as compared with their Il12rb2+/+ littermates." (PMID 38498592, 2024). "Our results indicate that the expression of IL6, IL12B, IL1R2, IL23R, IL12RB1 and IL12RB2 increased after DTMUV infection." (PMID 35585616, 2022). "The number of NK IL-12Rβ2 lymphocytes differed across the three groups (p = 0.002), with fewer NK IL-12Rβ2 lymphocytes in the septic group (p = 0.006) and the infection group (p = 0.003) than in the control group." (PMID 32560376, 2020). "On day 8 post-infection, WT P14 cells were more abundantly found in spleen, lungs and blood, followed by IL12Rβ2−/− and IFNAR−/− P14 cells." (PMID 32385253, 2020). "After infection, the expression of IL12Rβ2 was decreased in ILC1s from the liver, and in ILC1s and NCR+ILC3s from the small intestine in Runx3 cKO mice." (PMID 30258450, 2018). "Interestingly, 25 of 53 genes (47.1%) were uniquely downregulated in Il12rb2+/+ mice in response to C. rodentium 9 d after infection, but no genes were specifically downregulated in the colons of Il12rb2−/− mice following infection." (PMID 38498592, 2024). "In conclusion, the gene-expression signature predominant in livers of BALB/c mice 10 days after infection with L. infantum is characterized by the overrepresentation of IL12-mediated signaling events (FDR=0.003) with the strong upregulation of Il12rb2, Ifng, Nos2, Il12rb1, and Il12b." (PMID 34281214, 2021). "However, the expression of IL-12 receptor (IL-12Rβ2) differed significantly across the three groups (p = 0.004), with the IL-12Rβ2 expression lower in the infection group than in the control group (p = 0.003)." (PMID 32560376, 2020). "The expression of IL-12Rβ2 in NK cells differed significantly across the three groups (p = 0.008), with the NK cell IL-12Rβ2 expression lower in the septic group than in the control group (p = 0.05) and lower in the infection group than in the control group (p = 0.01)." (PMID 32560376, 2020). "Altogether, these findings indicated the indispensable requirement of IL-12Rβ2 signaling in the early resistance to C. rodentium (innate immune compartment), whereas the clearance of the infection (adaptive immune compartment) did not require functional IL-12Rβ2 signaling." (PMID 38498592, 2024).
adenocarcinoma (2 papers, 2009 to 2025). A common cancer characterized by the presence of malignant glandular cells. "Thirty/70 adenocarcinomas (42.9%), 21/49 of which were ADBF, 2/8 ADC and 7/13 BAC, were positive for IL-12Rβ2 expression." (PMID 19582164, 2009).
bacterial infection (2 papers, 2017 to 2018). "The second pattern was observed in two genes, IL-12p40 and IL-12Rβ2, which were progressively up-regulated upon bacterial infection." (PMID 28094307, 2017). "We found that ILC1s or NCR+ILC3s from both the liver and small intestine both expressed measurable levels of IL12Rβ2, IL18Rα, and IL15R after intracellular bacterial infection." (PMID 30258450, 2018).
infectious disease (2 papers, 2015 to 2024). A disorder directly resulting from the presence and activity of a microbial, viral, or parasitic agent in humans. "Aberrant expression of IL12RB2 has been reported in autoimmune and infectious diseases, implicating this gene as an important regulator of inflammation and immune defense." (PMID 25569146, 2015).
inflammation (1 paper, 2021). Aberrant reaction of the microcirculation characterized by movement of fluid and leukocytes from the blood into extravascular tissues. "Consequently, we concluded that Th17 cell-derived TGF-β1 regulates the stability of Th17 cells and inhibits the pathogenic conversion of Th17 cells into Th1-like exTh17 cells by regulating the expression of IL-12Rβ2 and IL-27Rα during CNS or intestinal inflammation in vivo." (PMID 34050263, 2021).
IL12RB2 also shares sentences with these, for which no sentence is quoted: asthma (2 papers); acute myelocytic leukemia (1); Alzheimer disease (1); ankylosing spondylitis (1); Anxiety (1); anxiety disorder (1); brain disorder (1); bronchioloalveolar carcinoma (1); cervical squamous cell carcinoma (1); chronic periodontitis (1); colorectal cancer (1); connective tissue disorder (1); depression (1); diabetes (1); fibrosarcoma (1); genetic disorders (1); hemorrhage (1); hepatitis B (1); HIV-1 infection (1); invasive breast carcinoma (1); ischemia (1); juvenile idiopathic arthritis (1); Kawasaki disease (1); lymphoma (1); malaria (1); Mendelian susceptibility to mycobacterial diseases (1); metastatic tumors (1); non-small cell lung carcinoma (1); osteoporosis (1); primary biliary cholangitis (1).
A further 11 diseases each share a sentence with IL12RB2 in 1 paper.